SNHG16 (small nucleolar RNA host gene 16)
Synonyms: ncRAN; Nbla12061; Nbla10727; ELNAT1
Gene: Long non-coding RNA gene on chromosome 17 (76,557,191 to 76,714,384, forward strand). Ensembl gene ENSG00000163597.
Gene Ontology:
Biological process: RNA processing
Cellular component: nucleolus
Diseases named in the same sentence as SNHG16 in open-access papers:
SNHG16 is named in the same sentence as 69 diseases in open-access papers, as found by Europe PMC text mining. Sharing a sentence is not in itself a finding about the gene and the disease. The quoted sentences say what the papers report.
neuroblastoma (21 papers, 2015 to 2025). Neuroblastoma (NB) is the most common solid, extracranial childhood tumor. "Small nucleolar RNA host gene 16 (SNHG16) is an lncRNA associated with poor neuroblastoma prognosis whose involvement in several other tumors and associated signaling pathways has been described." (PMID 38891878, 2024). "SNHG16 was regarded as an oncogene and associated with neuroblastoma, bladder cancer, colorectal cancer, esophageal squamous cell carcinoma, and hepatocellular carcinoma." (PMID 33102573, 2020). "Studies have indicated that SNHG16 knockdown can inhibit the proliferation of various malignant tumors, including renal clear-cell carcinoma, colorectal cancer, neuroblastoma, and osteosarcoma, while promoting apoptosis." (PMID 40427707, 2025). "In neuroblastoma, SNHG16 mediates oncogenic effects via the PAM and RAS/RAF/MEK/ERK signaling pathways." (PMID 38891878, 2024). "Small nucleolar RNA host gene 16 (SNHG16), located on 17q25.1, was first reported in aggressive neuroblastoma." (PMID 36221055, 2022). "SNHG16 is overexpressed in a variety of cancers, such as neuroblastoma, lung cancer, thyroid cancer, and breast cancer." (PMID 36506097, 2022). "LncRNA Small Nucleolar RNA Host Gene 16 (SNHG16), initially identified as an oncogene in neuroblastoma, is located on chromosome 17q25.1 and contains two splicing variants." (PMID 34760707, 2021). "For example, small nucleolar RNA host gene 16 (SNHG16) facilitated the development and progression of neuroblastoma by upregulating homeobox A7 (HOXA7) expression via sponging miR-128–3p." (PMID 34421622, 2021). "As well as that, NORAD, SNHG7, and SNHG16 have been shown to be involved in conferring this phenotype in neuroblastoma." (PMID 34178658, 2021). "Small nucleolar RNA host gene 16 (SNHG16) was originally identified as an oncogene in neuroblastoma, with a poor patient outcome when increased levels of SNHG16 were expressed." (PMID 33823834, 2021). "The lncRNA small nuclear RNA host gene 16 (SNHG16) (also named as non-coding RNA expressed in aggressive neuroblastoma [ncRAN]), which contains 2435 nts, is located on chromosome 17q25.1." (PMID 32944244, 2020). "SNHG16, also named ncRAN, was initially reported as a potent oncogene in neuroblastoma." (PMID 32944244, 2020). "In the present study, we also discovered SNHG16/miR-338-3p/PLK4 axis could regulate the activation of PI3K/AKT pathway in neuroblastoma cells." (PMID 32536824, 2020). "High SNHG16 amounts were shown to be significantly related to poor overall survival bladder cancer, cervical cancer, endometrial carcinoma, esophageal cancer, stomach cancer, glioma, liver cancer, neuroblastoma, lung cancer, osteosarcoma, and ovarian and pancreatic cancers." (PMID 32944244, 2020). "Although very little is known about the role of lncRNAs in NB, a study identified “non-coding RNA expressed in aggressive neuroblastoma” (ncRAN; also known as small nucleolar RNA host gene 16, SNHG16) and lncUSMycN, as being associated with aggressive MNA NBs and poor prognosis." (PMID 38069407, 2023). "SNHG16 affects the activation of the PI3K/AKT pathway in cisplatin‐resistant neuroblastoma cells, and SNHG16 does this by regulating PLK4 expression by sponging miR‐338‐3p and the SNHG16/miR‐338‐3p/PLK4 axis effect." (PMID 35592755, 2022). "Small nucleolar RNA host gene 16 (SNHG16), also known as noncoding RNA expressed in aggressive neuroblastoma, was newly identified as a potential oncogene in many cancers." (PMID 29416674, 2018). "Small nucleolar RNA host gene 16 (SNHG16) also known as non-coding RNA expressed in aggressive neuroblastoma (ncRAN), is located in chromosome 17q and its high expression is associated with poor outcome of NB patient." (PMID 27517149, 2016).
bladder cancer (20 papers, 2016 to 2025). "Lastly, the upregulation of SNHG16 in bladder cancer was revealed; it negatively regulates miR-98 expression, which contributes to bladder cancer malignancy through the miR-98/STAT3/Wnt/β-catenin pathway axis." (PMID 38872210, 2024). "Inhibition of SNHG16 expression can significantly suppress the proliferation, migration, and invasion of bladder cancer cells, and promote cell apoptosis, possibly through inhibition of the Wnt/β-catenin pathway." (PMID 37592177, 2023). "The overexpression of SNHG16 (ncRAN) is positively correlated with aggressive bladder cancer and the silencing of SNHG16 can improve chemotherapy sensitivity in BC cell lines." (PMID 27793008, 2016). "Moreover, SNHG16 was found to promote EMT process in bladder cancer via directly interacting with miR‐17‐5p,28 and it miR‐23b‐3p was found to be moderated by LncRNA HOTAIR to enhance the EMT process, resulting in acceleration of malignant HCC development." (PMID 32324343, 2020). "Knockdown of SNHG16 inhibits EMT in bladder cancer, colon cancer, esophageal cancer, cervical cancer, oral squamous cell carcinoma, gastric cancer, and hepatocellular carcinoma, and regulates EMT-associated molecules (upregulates E-cadherin, and downregulates N-cadherin and vimentin)." (PMID 32944244, 2020). "Furthermore, a shorter RFS was observed in bladder cancer patients with high expression of SNHG16 in serum, implying that expression of SNHG16 in serum was a hazardous factor for the recurrence of bladder cancer." (PMID 31632195, 2019). "Increased expression of SNHG16 usually predicted poor prognosis in multiple cancers including osteosarcoma, bladder cancer, esophagus cancer, non-small cell lung cancer (NSCLC), glioma, oral squamous cell carcinoma, hepatocellular carcinoma (HCC), breast cancer, and ovarian cancer." (PMID 31632195, 2019). "Indeed, SNHG16 was shown to be markedly elevated in plasma specimens from 26 bladder cancer cases vs. 15 control patients, as well as in serum samples from 120 bladder cancer cases vs. 52 healthy subjects." (PMID 32944244, 2020). "For instance, SNHG16 expression levels were significantly upregulated in osteosarcoma, glioma, colorectal adenocarcinoma, breast cancer, cervical cancer, ovarian cancer, bladder cancer, ESCC, NSCLC, oral squamous cell carcinoma, and acute lymphoblastic leukemia, but downregulated in HCC." (PMID 31632195, 2019). "The expression of SNHG16, MALAT1, and UCA1 were up-regulated in bladder cancer tissue, while the expression of YRNA1, YRNA3, YRNA4, YRNA5, and MEG3 were down-regulated." (PMID 29899709, 2018). "Small nucleolar RNA host gene 16 (SNHG16) was newly identified as a potential oncogene in lung cancer, breast cancer, bladder cancer and colorectal cancer." (PMID 29416674, 2018). "Up to now, it was reported that some lncRNAs was aberrantly expressed in bladder cancer, such as HULC, MALAT1, and SNHG16." (PMID 29899709, 2018). "The expression of H19, SNHG16 and UCA1 was significantly elevated in bladder cancer tissues, while PTENP1 and MEG3 were significantly decreased in bladder cancer tissues compared with adjacent normal tissues (P < 0.05)." (PMID 30285771, 2018).
breast carcinoma (17 papers, 2018 to 2025). "Out of the 13 available survival curve results, low expression of NEAT1 or high expression of SNHG16 was associated with significantly shorter survival in 626 breast cancer patients." (PMID 33494814, 2021). "Small nuclear RNA host gene 16 (SNHG16) is overexpressed in multiple cancers—including hepatocellular carcinoma, bladder cancer, breast cancer, and osteosarcoma—and is correlated with tumor progression and poor survival outcomes." (PMID 40429961, 2025). "SNHG16 is a novel cancer-related lncRNA and has been demonstrated to function as an oncogene in human breast cancer, gastric cancer, or hepatocellular cancer." (PMID 34722629, 2021). "In breast cancer, SNHG16 is upregulated and secreted by exosomes." (PMID 40429961, 2025). "In addition, upregulated CCND2, SNHG16, MYC, and GNAS levels were associated with accelerating cell cycle progression, as well as promoting growth and metastasis in lung cancer, breast cancer, and colon cancer." (PMID 37007962, 2023). "Overexpression of SNHG16 could promote the migration of breast cancer cells through modulating miR-98/E2F5 axis." (PMID 31781497, 2019). "In addition, SNHG16/miR-30a/RRM2 axis also accelerates breast cancer cell proliferation and promote cell invasion, while miR-30a regulates liver cell proliferation and apoptosis through the suppressor of cytokine signaling 1 (SOCS-1)/JAK/STAT signaling pathway in rats with sepsis." (PMID 34895038, 2021). "Small nucleolar RNA host gene 16 (SNHG16) has been reported as an oncogenic lncRNA in multiple cancers, such as colorectal cancer, non-small cell lung cancer, breast cancer, and clear cell renal cell carcinoma." (PMID 33435953, 2021). "High expressed SNHG16 can suppress hsa-miR-190b, which leads to increased expression of BCL11A, an oncogene in breast cancer." (PMID 33344235, 2020). "For example, SNHG16 competes with E2F5 to bind with miR-98, thus promoting breast cancer cell migration." (PMID 32242897, 2020). "Furthermore, a series of lncRNAs have been elucidated to serve as important prognostic hallmarks in numerous tumors, for instance, MALAT1 in breast cancer and digestive system cancer, XIST in various solid tumors, BCAR4 and SNHG16 in diverse human neoplasms." (PMID 33639865, 2021). "It is noteworthy that NEAT1 was decreased and SNHG16 was increased in breast cancer samples with MIR3613 deletion compared to the non-deletion group from TCGA breast cancer cohort." (PMID 33494814, 2021). "LncRNA small nucleolar RNA host gene 16 (SNHG16) is a cancer-related lncRNA, which was found to be elevated in diverse cancers, such as breast cancer, gastric cancer, osteosarcoma, and hepatocellular carcinoma, and acted as an oncogene to contribute to the drug resistance and development of cancers." (PMID 32536824, 2020).
colorectal cancer (17 papers, 2014 to 2025). A primary or metastatic malignant neoplasm that affects the colon or rectum. "Furthermore, small nucleolar RNA host gene 16 (SNHG16) was proposed to regulate the balance in an SNHG16/miR-200a ceRNET and was associated with regulation of malignancy potential of colorectal cancer cells." (PMID 35011635, 2021). "Moreover, the elevated expression of small nucleolar RNA host gene 16 (SNHG16) was found in colorectal cancer and tightly implicated in poor prognosis of patients." (PMID 33817285, 2020). "For instance, silencing of SNHG16, which is up-regulated in colorectal cancer, inhibited proliferation, increased apoptosis, and reduced cell migration." (PMID 28212545, 2017). "Contrast to the expression tendency in BC tissues, SNHG16 is down-regulated in colorectal cancer tissue." (PMID 27793008, 2016). "Yet, the role of SNHG16 in human colorectal cancer (CRC) still remains to be explored." (PMID 30962265, 2019). "In colorectal cancer (CRC), the reduced expression of SNHG16 impacts the genes that are involved in lipid metabolism." (PMID 36983670, 2023).
hepatocellular carcinoma (15 papers, 2019 to 2025). A malignant tumor that arises from hepatocytes. "SNHG16 has also been implicated to be involved in resistance to sorafenib, a drug that is widely used for treating hepatocellular carcinoma, and has been described as a potential biomarker of unfavorable prognosis in a recent meta-analysis of 5 studies." (PMID 39397388, 2025). "It has been discovered that the has-miR-186 is regulated by the SNHG16 gene and is involved in the proliferation, migration and invasion of hepatocellular carcinoma cells." (PMID 38678587, 2024). "SNHG16 is also reported to be downregulated in several other malignant tumors, such as hepatocellular carcinoma, and to inhibit tumor growth." (PMID 34722629, 2021). "In hepatocellular carcinoma, SNHG16 is highly expressed in HCC-resistant tissues and promotes HCC cell viability and autophagy while suppressing apoptosis by regulating the miR-23b-3p/EGR1 pathway." (PMID 33435953, 2021). "Function assays showed that SNHG16 knockdown suppressed cell proliferation, arrested cell cycle transition from G1 to S phase, and promoted cell apoptosis in MM cells, similar with the roles of SNHG16 in hepatocellular carcinoma and pancreatic cancer." (PMID 32025219, 2020). "SNHG16 contributes to chemoresistance in hepatocellular carcinoma." (PMID 32944244, 2020). "Additionally, SNHG16 may contribute to sorafenib resistance in hepatocellular carcinoma via the EGFR1/miR-23b-3p and miR-140-5p pathways." (PMID 40427707, 2025). "In hepatocellular carcinoma (HCC), SNHG16 has diverse oncogenic as well as tumor suppressor roles." (PMID 34671603, 2021).
glioma (14 papers, 2019 to 2025). A benign or malignant brain and spinal cord tumor that arises from glial cells (astrocytes, oligodendrocytes, ependymal cells). "For instance, high expression of POLR2J4 has been reported to be associated with poor prognosis in various malignancies, while SNHG16 promotes glioma tumorigenesis via activation of the PI3K/AKT pathway and the miR-373/EGFR axis." (PMID 40661083, 2025). "Knockdown of SNHG16 suppresses the viability of glioma cells and promotes apoptosis by regulating the expression of B-cell lymphoma 2 family (Bcl-2) proteins and activating the PI3K/Akt signaling pathway." (PMID 33980320, 2021). "In summary, this study identifies SYDE1 as an oncogene in gliomas that can regulate the proliferation and migration of glioma cells and is predicted to interact with the SNHG16/hsa-miR-520e axis." (PMID 34722629, 2021). "That is, upregulated SYDE1 in gliomas can potentially activate SNHG16 expression to facilitate the onset and progression of gliomas." (PMID 34722629, 2021). "The small nucleolar RNA host gene 16 (SNHG16) lncRNA is highly expressed in gliomas and is correlated with short survival and poor clinicopathologic features." (PMID 33980320, 2021). "The ceRNA role of SNHG16, which is overexpressed in glioma, also promotes the malignancy through the enhancement of endogenous target gene, E2F1 via sponging of miR-20a-5p." (PMID 33980320, 2021). "Considering the versatile role of SNHG16 in tumor development, we examined SNHG16 expression in our study and found that the SNHG16 level was significantly increased in gliomas." (PMID 34722629, 2021). "Here, besides studies reporting the roles of SNHG16 in glioma tumorigenesis, we provided more evidence of SNHG16 as oncogene to promote GBM invasion." (PMID 31487431, 2019). "The forest plot shows that EPB41L4A.AS1, GDNF.AS1, HAR1A, LINC00237, SLC25A21.AS1, SNA13.AS1, and WDFY3.AS2 are the protective factors with HR < 1, while LINC00092, LINC00265, LINC00339, LINC00665, PAXIP1.AS2, SNHG16, SNHG9 and SOCS2.AS1 are risk factors with HR>1 in glioma patients." (PMID 35273128, 2022). "Moreover, SNHG16 promotes glioma tumorigenesis by acting as the ceRNA that upregulates the expression of the miR-4518 targeted gene, protein arginine methyltransferase 5 (PRMT5) by directly sponging miR-4518." (PMID 33980320, 2021). "Additionally, SNHG16 upregulation was also shown to be related to poor progression free survival (PFS) in glioma, liver cancer, and lung cancer." (PMID 32944244, 2020). "Compared to normal tissues, the expression levels of AL590666.2, POLR2J4, SNHG16, AL359541.1, AC004943.2, and SOX21-AS1 were significantly upregulated in glioma tissues." (PMID 40661083, 2025). "The results revealed that AL590666.2, POLR2J4, SNHG16, AL359541.1, AC004943.2, and SOX21-AS1 were significantly upregulated in glioma tissues compared to normal tissues." (PMID 40661083, 2025). "Results show the mean expression levels of LINC00665, LINC00339, SNHG16, PAXIPI.AS2 and LINC00092 in the glioma tissues are higher than those in the NBTs." (PMID 35273128, 2022). "Thus, we predicted that SNHG16 might play a key role in glioma." (PMID 33817285, 2020). "Finally, the expression levels of AL590666.2, POLR2J4, SNHG16, AL359541.1, AC004943.2, and SOX21-AS1 were significantly elevated in glioma cell lines compared to corresponding normal cell lines." (PMID 40661083, 2025). "Additionally, small nucleolar RNA host gene 16 (SNHG16) suppressed the expression of p21, caspase-3 and caspase-9, while promoting cyclin-D1 and cyclin-B1 expression to inhibit apoptosis in glioma cells." (PMID 35601497, 2022). "Not surprisingly, our data confirmed that the lncRNA SNHG16 functions as an oncogene, contributing to glioma progression by acting as miR-424-5p sponge." (PMID 33817285, 2020).
osteosarcoma (11 papers, 2019 to 2025). A usually aggressive malignant bone-forming mesenchymal neoplasm, predominantly affecting adolescents and young adults. "Under this premise, Zhu and colleagues found that the lncRNA small nucleolar RNA host gene 16 (SNHG16) was highly expressed in osteosarcoma cell lines and tissues." (PMID 35011442, 2021). "Conversely, researchers observed that the downregulation of SNHG16 enhances osteosarcoma cell proliferation." (PMID 35011442, 2021). "Again, a recent work reported a link between decreased levels of miR-205 and high expression of lncRNA small nucleolar RNA host gene 16 (SNHG16) in osteosarcoma tissues." (PMID 33191398, 2020). "In addition, SNHG16 has be suggested to promote EMT by upregulating ITGA6 through a miR-488 inhibition in osteosarcoma." (PMID 34458149, 2021). "Finally, SNHG16 can facilitate EMT of osteosarcoma cells through miR-488/ITGA6 axis." (PMID 34671603, 2021). "Recent studies have shown SNHG1, SNHG5, SNHG16, and SNHG20 to be overexpressed in osteosarcoma tissues and play vital roles in promoting tumour progression." (PMID 37278038, 2023).
cervical cancer (9 papers, 2019 to 2023). A primary or metastatic malignant neoplasm involving the cervix. "As a transcription factor, SPI1 can be recruited by small nucleolar RNA host gene 16 (SNHG16) to regulate downstream gene expression, thus promoting the biological behaviour of cervical cancer cells." (PMID 37539493, 2023). "The recently identified lncRNA, small nucleolar RNA host gene 16 (SNHG16), has been found to be involved in the progression of number of human cancers like colon and cervical cancers." (PMID 35646120, 2022). "SNHG16 is highly expressed in cervical cancer tissues, and is closely related to the TNM stage, tumor size, distant metastasis and survival prognosis." (PMID 37303939, 2021). "In cervical cancer cells, SNHG16 has been found to recruit transcriptional factor SPI1 to increase expression of PARP9, thus promoting malignant behaviors of cells." (PMID 34671603, 2021). "SNHG16 has been reported to play a functional role in the progression of numerous different types of cancer, such as gastric cancer and cervical cancer." (PMID 33823834, 2021). "For example, SNHG16 can recruit the SPI1 protein to promote the transcriptional activation of the PARP9 promoter in cervical cancer." (PMID 37303939, 2021). "In cervical cancer, SNHG16 overexpression is related to tumor size and differentiation, as well as lymph node metastasis and FIGO stage." (PMID 32944244, 2020). "A previous study discovered that lncRNA small nucleolar RNA host gene 16 upregulated poly(ADP-ribose) polymerase family member 9 expression by recruiting the transcription factor, SPI1, to promote the tumorigenicity of cervical cancer cells." (PMID 34738863, 2021).